PIRT (phosphoinositide interacting regulator of transient receptor potential channels)
Description:
Regulatory subunit of TRPV1, a molecular sensor of noxious heat and capsaicin. Positively regulates TRPV1 channel activity via phosphatidylinositol 4,5-bisphosphate (PIP2). Binds various phosphoinositide, including phosphatidylinositol 4,5-bisphosphate (PIP2), but not phosphatidylinositol (PI) (By similarity).
Tractability: Antibody: UniProt predicts a signal peptide or a membrane-spanning region; its Gene Ontology location is reachable by antibodies, with medium confidence.
Gene: Protein-coding gene on chromosome 17 (10,822,470 to 10,838,087, reverse strand). Ensembl gene ENSG00000233670.
Subcellular location: Membrane
Subcellular location (Human Protein Atlas): Cytosol; Plasma membrane
Gene Ontology:
Molecular function: phosphatidylinositol bisphosphate binding; transmembrane transporter binding; phosphatidylinositol-3,4,5-trisphosphate binding
Biological process: regulation of sensory perception of pain
Cellular component: plasma membrane; membrane
Genetic constraint (gnomAD): Loss-of-function variants: 6 observed, 7.47 expected, observed/expected ratio (o/e) 0.8, 90% interval 0.44 to 1.55. That is too few expected variants to judge how well the gene tolerates losing a copy. Missense variants: 170 observed, 175.46 expected, observed/expected ratio (o/e) 0.97, 90% interval 0.85 to 1.1. Synonymous variants: 78 observed, 70.85 expected, observed/expected ratio (o/e) 1.1, 90% interval 0.92 to 1.33.
Homologues: Orthologues: chimpanzee PIRT (100% identical), macaque PIRT (97% identical), dog PIRT (89% identical), pig PIRT (83% identical), guinea pig PIRT (81% identical), rabbit PIRT (80% identical), rat Pirt (80% identical), mouse Pirt (78% identical), tropical clawed frog pirt (45% identical). Paralogues in human: TMEM100 (18% identical).
Diseases named in the same sentence as PIRT in open-access papers:
PIRT is named in the same sentence as 2 diseases in open-access papers, as found by Europe PMC text mining. Sharing a sentence is not in itself a finding about the gene and the disease. The quoted sentences say what the papers report.
breast carcinoma (1 paper, 2020). "Our MST and NMR data show that PIRT binds tightly to β-estradiol and induce some evidence of conformational change in the HSQC, which suggests PIRT might play a role between TRP channels with β-estradiol in breast cancer cells." (PMID 32245175, 2020).
Obesity (1 paper, 2020). Accumulation of substantial excess body fat. "Supporting the role of PIRT in sex-dependent function, a recent study of PIRT knock-out (-/-) mice indicate that there are subtle PIRT-dependent impacts in metabolism and obesity that are female-specific." (PMID 32245175, 2020).